MYCT1 (MYC target 1)
Diseases named in the same sentence as MYCT1 in open-access papers (continued):
Sharing a sentence is not in itself a finding about the gene and the disease.
lymphoma (1 paper, 2024). A malignant (clonal) proliferation of B- lymphocytes or T- lymphocytes which involves the lymph nodes, bone marrow and/or extranodal sites. "The findings provide clues and a basis for in-depth studies of MYCT1 in the diagnosis, treatment and prognosis of lymphoma." (PMID 38172714, 2024). "And the study provides clues and basis for the in-depth studies of MYCT1 in the diagnosis, treatment and prognosis of lymphoma." (PMID 38172714, 2024). "This experiment is the first to study the function and mechanism of MYCT1 in lymphoma, which provides a new target for further study of the pathogenesis and early diagnosis and treatment of lymphoma." (PMID 38172714, 2024). "MYCT1 overexpression reduced the proliferation of DLBCL cells and blocked the cells in G0/G1, which played a significant negative regulatory role in DLBCL cells, once again confirming the role of MYCT1 as a tumor suppressor gene in lymphoma." (PMID 38172714, 2024). "In the analysis of abnormal karyotype of lymphoma patients, three smallest overlap regions were found, in which MYCT1 was located." (PMID 38172714, 2024). "Immunohistochemical results showed that MYCT1 was expressed in the nucleus and cytoplasm of lymphoma, mainly in the nucleus, and was expressed at low levels and was positive." (PMID 38172714, 2024). "Through a series of experiments, we proved the regulation of the MYCT1-MAX-RUNX1 signaling pathway in DLBCL cells and confirmed that MYCT1 plays the role of its tumor suppressor gene in lymphoma." (PMID 38172714, 2024). "The study of clinical specimens has suggested that MYCT1 expression is reduced in lymphoma and thus may play a role as a tumor suppressor gene in lymphoma." (PMID 38172714, 2024). "MYCT1 negatively correlated with RUNX1 in lymphoma tissues of the patients." (PMID 38172714, 2024). "MYCT1 was positive in 10 of 27 patients with lymphoma, with a positive rate of 37%." (PMID 38172714, 2024). "Therefore, effects of MYCT1 on migration and drug resistance of lymphoma cells needs further study." (PMID 38172714, 2024). "MYCT1 and RUNX1 site-specific FISH probes were used to detect the copy number of MYCT1 and RUNX1 DNA in bone marrow samples of 78 patients with malignant lymphoma with abnormal karyotypes." (PMID 38172714, 2024). "The expression levels of MYCT1 and RUNX1 mRNA in paraffin-embedded tissues of 27 cases of lymphoma were detected by qPCR." (PMID 38172714, 2024). "The results showed that compared with the reactive lymphadenitis control group, the mRNA expression levels of MYCT1 and RUNX1 in lymphoma paraffin-embedded tissues were significantly lower and higher, respectively." (PMID 38172714, 2024). "The expression levels of MYCT1 and RUNX1 mRNA in the bone marrow of 12 lymphoma patients with bone marrow infiltration were detected by qPCR." (PMID 38172714, 2024). "The results showed that compared with the normal bone marrow control group, the mRNA expression levels of MYCT1 and RUNX1 in the bone marrow of lymphoma patients were significantly lower and higher, respectively." (PMID 38172714, 2024). "Meanwhile, deletion of the MYCT1 locus and amplification of the RUNX1 locus occurred in lymphoma cell karyotypes, suggesting that MYCT1 and RUNX1 have opposite roles in lymphoma." (PMID 38172714, 2024). "Moreover, we also found that MYCT1 and RUNX1 were downregulated and upregulated in lymphoma, respectively." (PMID 38172714, 2024). "MYCT1 is the first tumor suppressor gene cloned by our research team, but its studies relating to the occurrence and development of lymphoma have not been reported." (PMID 38172714, 2024). "Since MYCT1 and MAX are widely expressed in a variety of normal tissues, we speculate that MYCT1 may regulate the expression of RUNX1 at the transcriptional level through interaction with MAX, participating in the occurrence and development of lymphoma." (PMID 38172714, 2024).
lymphoma (continued). "At present, there has been no report on whether MYCT1 can affect the stability of chromosome karyotypes or its relationship with the occurrence and development of lymphoma." (PMID 38172714, 2024). "However, the role and mechanism of MYCT1 in lymphoma, including DLBCL, have not been reported." (PMID 38172714, 2024).
steatosis (1 paper, 2022). Increased lipid within the cytoplasm of cells. "Strong associations with steatosis were observed for rs2519093 (ABO) [AOR = 8.51 (1.01–71.72), p = 0.049] and rs17710008 (MYCT1) [AOR = 2.75 (1.00–7.57), p = 0.050]." (PMID 36386790, 2022).
tumor (24 papers, 2011 to 2025). "Myct1 deficiency in mouse tumor models decreases angiogenesis and increases antitumor immunity, thereby limiting tumor growth." (PMID 38580870, 2024). "Other proteins such as MYCT1, expressed almost exclusively in tumour associated endothelial cells, have been identified to be regulators of angiogenesis." (PMID 35814453, 2022). "Among the candidate target genes, MYCT1 showed a strong association with tumor cell migration." (PMID 39744435, 2025). "Several studies have demonstrated that MYCT1 is associated with tumor cell migration." (PMID 39744435, 2025). "Importantly, Myct1 inhibition (i.e., Myct1 global knockout and Myct1 endothelial knockout) led to a reduction in tumor growth and angiogenesis, reminiscent of Etv2-deficient tumor vessel." (PMID 36927793, 2023). "Knockdown of MYCT1 and treatment with LiCl independently inhibited tumor growth and volume, while the combination of MYCT1 knockdown with LiCl was more effective than either treatment alone." (PMID 39744435, 2025). "Previously, we showed that MYCT1, the first tumor suppressor gene cloned in our laboratory, plays an important role in the occurrence and development of many kinds of tumors." (PMID 38172714, 2024). "The authors found that Myct1 expression is crucial for cancer progression through the regulation of both tumor angiogenesis and tumor immunity." (PMID 36834641, 2023). "Lung and sarcoma tumor xenografts were shown to be susceptible to siRNA polyplexes against factors that control tumor angiogenesis (ETV-2 and MYCT1) and the immunosuppressive tumor microenvironment." (PMID 37298407, 2023). "MYCT1 has been shown to function as a tumor suppressor in various tumors, but its role in metabolism has never been reported." (PMID 35281731, 2022). "Translation control of specific genes mediated by MYCT1/RACK1 provides a precise means to fine-tune glycogen shunt assisting tumor cells to achieve metabolic homeostasis." (PMID 35281731, 2022). "Another gene with near exclusive endothelial cell expression, Myct1, was shown to be critical in the context of tumour angiogenesis where targeting Myct1 showed promises in the tumour vessel normalisation." (PMID 36444960, 2022). "Targeting MYCT1 has been demonstrated to be synergistic with checkpoint blockade in inhibiting tumour growth in pre-clinical models." (PMID 35814453, 2022). "Even recently, Myct1 was identified as a transcription factor in the tumor endothelium and was shown to play a dual role in tumor angiogenesis and tumor immunity." (PMID 34503262, 2021). "MYCT1, previously named MTLC, is a novel candidate tumor suppressor gene and a direct downstream gene of c-Myc in LSCC." (PMID 32047362, 2020). "Twenty-one days after tumor cell inoculum, marked reduction in tumor weight was induced by MYCT1 overexpression (P < 0.01 versus Lv-NC)." (PMID 30283340, 2018). "Western blot results showed that the MYCT1 expression was significantly increased in the tumor injected with Lv-MYCT1 (P < 0.01 versus Lv-NC)." (PMID 30283340, 2018). "We were not able to confirm the subcellular localization of endogenous MYCT1 in several tumour cell lines, including HeLa, 293T, SW480, HCT116 and A549 cells, using commercial or homemade MYCT1 antibody (data not shown)." (PMID 26710964, 2016). "The consistent transcriptional activities of this 864 bp promoter in tumor and normal cells we tested indicated that ubiquitous E-box elements are involved in regulation of MYCT1-TV gene transcription." (PMID 21998677, 2011). "In addition, MYCT1 facilitates cross-talk between angiogenesis and immunity within the tumor microenvironment." (PMID 38674024, 2024). "Interestingly, upregulated genes MYCT1, and SAMD9 have been implicated as tumor suppressors in other cancers such as hematologic malignancies." (PMID 38589567, 2024).
tumor (continued). "MYCT1, a direct c-Myc target gene, regulates numerous downstream genes and inhibits epithelial−mesenchymal transition, migration, and apoptosis in various cancer cells, suggesting that it acts as a tumor suppressor." (PMID 37444464, 2023). "Moreover, when Myct1 targeting is combined with anti-PD-1 treatment, the tumor regression is complete, with a significant long-term survival of BC-bearing mice." (PMID 36834641, 2023). "Our data reveal a critical role of MYCT1 as a switch for the glycogen shunt in tumor cells." (PMID 35281731, 2022). "Unexpectedly, the Myct1 KO mice displayed progressive liver glycogen accumulation instead of tumor-related phenotypes, and this finding was consistent with the iTRAQ proteomics data obtained from our tumor research, showing enrichment of a series of glycogen synthesis enzymes (data not shown)." (PMID 35281731, 2022). "Notably, the metabolite quantities in control groups showed significant variations among three different cells, and higher levels were found in tumor cells, particularly in those with high MYCT1 expression." (PMID 35281731, 2022). "The deletion of Myct1 directed more carbon sources to glycogen stored in cells and reduced the diversion to glycolysis through G6P, which is quite similar to the opposite pattern of glycogen shunt in tumor cells." (PMID 35281731, 2022). "Finally, in BALB/c nude mice bearing xenograft tumors generated by HL-60 and KG-1a cells, we noted that the intratumoral injection of MYCT1 lentivirus repressed tumor growth and led to massive apoptosis." (PMID 30283340, 2018). "MYCT1 plays a tumor-suppressive role, and it may serve as a promising target for the genetic therapeutic strategy in treating AML." (PMID 30283340, 2018). "Interestingly, we found EGF accelerated tumour cell migration more greatly in the presence of MYCT1 than EV or MYCT1(ΔTM)." (PMID 26710964, 2016). "Furthermore, when we compare the differentially expressed genes between KPT-330 treated cells as compared to cells with TRIP13 suppression, we find several potential tumor suppressors such as MYCT1 and SAMD9, a gene having antiproliferative properties, whose expression increases." (PMID 38589567, 2024). "Here we speculate that MYCT1 may act as a tumor suppressor in AML carcinogenesis." (PMID 30283340, 2018). "We suppose that MYCT1 might enhance the tumour cell migration through inhibiting CKAP4 function." (PMID 26710964, 2016). "To examine whether MYCT1 affects tumour cell migration, we performed a transwell migration assay." (PMID 26710964, 2016). "The translational upregulation of PGM1, UGP2 and GSK3A mediated by MYCT1 and RACK1 adjusted the flux of glycogen synthesis and glycogen shunt, which is crucial for modulating the tumor metabolic reprogramming." (PMID 35281731, 2022). "MYC target 1 (MYCT1), a direct target gene of MYC, is a novel candidate tumor suppressor gene cloned from LSCC." (PMID 33917482, 2021). "We found that overexpression of MYCT1 abolished CKAP4‐mediated up‐regulation of E‐cadherin and CKAP4 interference‐induced tumour cell migration." (PMID 26710964, 2016). "In this study, 12 potential methylated sites in the MYCT1 promoter region were predicted in silico, and hypermethylation was observed in 10 LSCC tumor samples and the Hep2 cancer cells by BSP-based sequencing." (PMID 22672838, 2012). "Non-tumor components included endothelial cells (expressing VWF, CDH5, ECSCR, SLCO2A1, and MYCT1), pericytes (marked by RGS5, MCAM, and PDGFRB), normal oligodendrocytes (showing PTGDS, MBP, TF, and MOG expression), and TAMs (identified by CD14, AIF1, FCER1G, FCGR3A, TYROBP, and CSF1R)." (PMID 41394801, 2025).
tumor (continued). "Myc target protein 1 (Myct1), which is almost explicitly expressed in endothelial cells, interacts with the tight junction protein zona occludens 1 (ZO1) of cancer cells to promote a unique tumor niche for cancer angiogenesis and anti-immunity." (PMID 36632469, 2023). "Overexpression of MYCT1, not MYCT1 (ΔTM), decreased cell viability under serum deprivation and increased tumour cell migration ability." (PMID 26710964, 2016). "Similar to MYCT1, YY1 may act as an oncogene or a tumor suppressor in different cancer types." (PMID 28485541, 2017).
cancer (12 papers, 2010 to 2025). A tumor composed of atypical neoplastic, often pleomorphic cells that invade other tissues. "In addition, we demonstrated that the point mutation (A88D), which exists in a clinical cancer sample, changed the localization and function of MYCT1." (PMID 26710964, 2016). "MYCT1 plays inhibitory roles in controlling the growth, adhesion, transformation, apoptosis and migration in various cancers 38-43." (PMID 38021164, 2023). "Studies have showed that MYCT1 plays an important role in tumorigenesis either as a tumor suppressor gene or an oncogene in different tumors, implying that MYCT1 function in cancer is tissue‐specific." (PMID 28485541, 2017). "We assessed the expression levels of MYCT1-TV/MYCT1 with respect to clinical characteristics (age, sex and cancer stage)." (PMID 21998677, 2011). "Studies have shown that MYCT1 is aberrantly expressed in various cancers and affects key biological processes such as proliferation, apoptosis, migration, genomic instability, and differentiation in cancer cells." (PMID 39744435, 2025). "Therefore, study on MYCT1 regulation network helps us to understand the tissue‐specific manner of MYCT1 in cancer." (PMID 28485541, 2017). "We observed that methylation of the CGCG site (−695 to −692) significantly correlated with cancer cell differentiation but did not correlate with age, gender and TNM staging, suggesting that MYCT1 methylation could inhibit cancer cell differentiation." (PMID 22672838, 2012). "In summary, this study concluded that hypermethylation contributed to the transcriptional down-regulation of MYCT1 and could inhibit cancer cell differentiation in LSCC." (PMID 22672838, 2012). "However, both MYCT1-TV and MYCT1 displayed lower expression in cancer tissues than that in adjacent normal tissues." (PMID 21998677, 2011). "Thus we inferred that MYCT1-TV/MYCT1 may silence through MYCT1-TV/MYCT1 promoter methylation in the absence of c-Myc overexpression, which is associated with cancer progression." (PMID 21998677, 2011). "Through negative modulation of GSK3β, MYCT1, Fascin actin-bundling protein 1 (FSCN1), and TFF1, miR-632 modulated the WNT/β-catenin pathway and subsequently promoted cancer cell migration, invasion, proliferation, tube formation, and endothelial cell recruitment." (PMID 35242169, 2022). "However, there was a significantly lower MYCT1 level in the cancer tissues from patients with metastasis than those without metastasis (P < 0.01)." (PMID 28485541, 2017). "However, the molecular mechanism of MYCT1 in cancer migration invasion has not been delineated." (PMID 33680912, 2020).
infection (2 papers, 2018 to 2022). The state of being infected such as from the introduction of a foreign agent such as serum, vaccine, antigenic substance or organism. "In contrast, Asb2 and Myct1 genes were both downregulated in the UB samples at both, 1 wk and 4 wks time points after infection." (PMID 36490282, 2022). "Overexpression of MYCT1 by lentivirus infection significantly suppresses proliferation and induces apoptosis of AML cells both in vitro and in vivo." (PMID 30283340, 2018).
MYCT1 also shares sentences with these, for which no sentence is quoted: acute myeloid leukaemia (2 papers); colorectal cancer (1); diabetes (1); ischemia (1); liver fibrosis (1); lung squamous cell carcinoma (1); lymph node metastasis (1); metabolic disorders (1); Myelodysplasia (1).